RAVER1 (ribonucleoprotein, PTB binding 1)
Description:
Cooperates with PTBP1 to modulate regulated alternative splicing events. Promotes exon skipping. Cooperates with PTBP1 to modulate switching between mutually exclusive exons during maturation of the TPM1 pre-mRNA (By similarity).
Synonyms: KIAA1978
Gene: Protein-coding gene on chromosome 19 (10,316,212 to 10,333,548, reverse strand). Ensembl gene ENSG00000161847.
Subcellular location: Nucleus; Cytoplasm
Subcellular location (Human Protein Atlas): Nucleoplasm
Genetic constraint (gnomAD): Loss-of-function variants: 31 observed, 47.02 expected, observed/expected ratio (o/e) 0.66, 90% interval 0.49 to 0.89. The upper end of that interval is the gene's LOEUF score, 0.89, which puts it in group 3 of 6, group 1 being the genes least tolerant of losing a copy. Missense variants: 871 observed, 838.64 expected, observed/expected ratio (o/e) 1.04, 90% interval 0.98 to 1.1. Synonymous variants: 441 observed, 383.94 expected, observed/expected ratio (o/e) 1.15, 90% interval 1.06 to 1.24.
Homologues: Orthologues: chimpanzee RAVER1 (100% identical), macaque RAVER1 (98% identical), pig RAVER1 (94% identical), dog RAVER1 (93% identical), guinea pig RAVER1 (91% identical), rat Raver1 (89% identical), mouse Raver1 (88% identical), rabbit RAVER1 (82% identical), tropical clawed frog raver1 (56% identical), zebrafish raver1 (49% identical), Drosophila melanogaster nito (10% identical). Paralogues in human: RAVER2 (37% identical), SPEN (20% identical), RBM15 (13% identical), SFPQ (12% identical), RBM15B (12% identical), NONO (11% identical), PSPC1 (11% identical).
Diseases named in the same sentence as RAVER1 in open-access papers:
RAVER1 is named in the same sentence as 15 diseases in open-access papers, as found by Europe PMC text mining. Sharing a sentence is not in itself a finding about the gene and the disease. The quoted sentences say what the papers report.
COVID-19 (7 papers, 2022 to 2025). A disease caused by infection with severe acute respiratory syndrome coronavirus 2. "In contrast to some of the data in the literature, the RAVER1 rs74956615 minor allele was more common in the COVID-19 patients than the EU average." (PMID 39752416, 2025). "Regarding the genetic polymorphisms, a higher allele frequency of the LZTFL1 and IFNAR2 minor variants significantly correlated with greater COVID-19 disease susceptibility (hospitalization) and severity, and a similar tendency was observed for the RAVER1 and the MUC5B variants." (PMID 39752416, 2025). "A deficiency in RAVER1 may lead to increased susceptibility of the host to COVID-19, potentially resulting in a more severe progression of the disease following infection." (PMID 40034745, 2025). "In COVID-19 patients who also had type 2 diabetes, our results indicated that patients carrying the minor variants of LZTFL1 and RAVER1 (and probably also IFNAR2 and MUC5B) are more likely to have hospitalization-requiring COVID-19 than the general population." (PMID 39752416, 2025). "Our present study analysing COVID-19 GWAS loci led to the identification of LZTFL1 and RAVER1 as influencing COVID-19 disease severity." (PMID 34998241, 2022). "Patients with risk alleles of rs11385942 and rs74956615 may be susceptible to critical illness in COVID-19 in part through weakened airway viral clearance via LZTFL1-mediated ciliogenesis and diminished antiviral immune response via the MDA5/RAVER1 pathway, respectively." (PMID 34998241, 2022).
type 2 diabetes (2 papers, 2019 to 2025). "Indeed, dysregulation of RAVER1 and RBM3 has been recently related with the development of non-alcoholic fatty liver disease, while RAVER1 has been found to be dysregulated in patients with cardiovascular disease at higher risk of type-2 diabetes development." (PMID 31561558, 2019).
Viral infection (2 papers, 2018 to 2022). "Viral infection, poly (I:C), or LPS challenge can evoke nuclear export of high-mobility group box (HMGB) proteins and ribonucleoprotein PTB-binding 1 (Raver1)." (PMID 29677136, 2018).
endothelial dysfunction (1 paper, 2025). In vascular diseases, endothelial dysfunction is a systemic pathological state of the endothelium (the inner lining of blood vessels) and can be broadly defined as an imbalance between vasodilating and vasoconstricting substances produced by (or acting on) the endothelium. "We also identified potential target genes, including those involved in inflammation signaling (CARM1), endothelial dysfunction (INTS12), and antiviral immune response (RAVER1), which may require further investigation." (PMID 40034745, 2025).
PRLomas (1 paper, 2019). "However, PLS-DA analysis neatly revealed a different expression pattern between PRLomas and NPs, and VIP score analysis identified three components with high capacity to discriminate between both populations (RAVER1, MAGOH, and RNU11)." (PMID 31561558, 2019).
tumor (2 papers, 2024). "Patients #5, #6, and #7 (without tumor samples) showed an overlap of four genes (SORL1, PTPRC, MIR6819, and NAMPT), while #6 and #7 also shared five genes (CELF2, EDEM3, SMCHD1, RAVER1, and CXCR1)." (PMID 39001407, 2024).
RAVER1 also shares sentences with these, for which no sentence is quoted: cardiovascular disease (1 paper); Crohn disease (1); depression (1); gout (1); infection (1); inflammation (1); malaria (1); non-alcoholic fatty liver disease (1); psoriasis (1).